PRDM14 (PR/SET domain 14)
Description:
Transcription factor that has both positive and negative roles on transcription. Required for the maintenance of embryonic stem cell identity and the reacquisition of pluripotency in somatic cells. May play an essential role in germ cell development at 2 levels: the reacquisition of potential pluripotency, including SOX2 up-regulation, and successful epigenetic reprogramming, characterized by EHMT1 repression. Its association with CBFA2T2 is required for the functions in pluripotency and germ cell formation (By similarity). Directly up-regulates the expression of pluripotency gene POU5F1 through its proximal enhancer. Binds to the DNA consensus sequence 5'-GGTC[TC]CTAA-3'.
Synonyms: PFM11
Tractability: PROTAC: ubiquitination databases record sites on it.
Target class: Enzyme; Transferase
Gene: Protein-coding gene on chromosome 8 (70,049,063 to 70,072,782, reverse strand). Ensembl gene ENSG00000147596.
Subcellular location: Nucleus
Subcellular location (Human Protein Atlas): Nucleoplasm; Vesicles
Pathways (Reactome):
Developmental Biology: Transcriptional regulation of pluripotent stem cells
Gene Ontology:
Molecular function: protein binding; RNA polymerase II transcription regulatory region sequence-specific DNA binding; chromatin DNA binding; histone methyltransferase binding; methyltransferase regulator activity; RNA binding
Biological process: regulation of transcription by RNA polymerase II; positive regulation of flagellated sperm motility; positive regulation of stem cell population maintenance
Cellular component: nucleoplasm; nucleus
Genetic constraint (gnomAD): Loss-of-function variants: 15 observed, 43.13 expected, observed/expected ratio (o/e) 0.35, 90% interval 0.23 to 0.54. The upper end of that interval is the gene's LOEUF score, 0.54, which puts it in group 2 of 6, group 1 being the genes least tolerant of losing a copy. Missense variants: 509 observed, 657.86 expected, observed/expected ratio (o/e) 0.77, 90% interval 0.72 to 0.83. Synonymous variants: 243 observed, 254.24 expected, observed/expected ratio (o/e) 0.96, 90% interval 0.86 to 1.06.
Homologues: Orthologues: chimpanzee PRDM14 (100% identical), macaque PRDM14 (97% identical), dog PRDM14 (80% identical), rabbit PRDM14 (80% identical), pig PRDM14 (76% identical), rat Prdm14 (71% identical), mouse Prdm14 (69% identical), guinea pig PRDM14 (65% identical), tropical clawed frog prdm14 (52% identical), zebrafish prdm14 (48% identical). Paralogues in human: PRDM6 (25% identical), PRDM1 (16% identical), ZNF362 (15% identical), HIC1 (15% identical), PRDM10 (14% identical), ZBTB16 (14% identical), ZBTB20 (14% identical), ZNF384 (14% identical), ZNF76 (14% identical), HIC2 (13% identical), ZNF143 (13% identical), ZBTB1 (13% identical), and 24 more.
Diseases named in the same sentence as PRDM14 in open-access papers:
PRDM14 is named in the same sentence as 52 diseases in open-access papers, as found by Europe PMC text mining. Sharing a sentence is not in itself a finding about the gene and the disease. The quoted sentences say what the papers report.
breast cancer (17 papers, 2008 to 2023). A primary or metastatic malignant neoplasm involving the breast. "We showed that PRDM14 has similar actions in breast cancer cells: PRDM14 was associated with the ‘activating’ H3K4me3 modification and reduced methylation of proto-oncogene and stemness gene promoters in breast cancer cells." (PMID 28423353, 2017). "A retrospective study showed that PRDM14 is frequently overexpressed in breast cancers and that its overexpression is often associated with gene amplification." (PMID 27688749, 2016). "Although PRDM14 has been implicated in human breast cancer, a mouse model misexpressing Prdm14 in the mammary gland has not been developed." (PMID 24046360, 2013). "Expression of PRDM14 is tightly regulated and typically limited to ESCs and primordial germ cells; however, aberrant expression is associated with tumor initiation in a wide variety of human cancers, including breast cancer and leukemia." (PMID 24046360, 2013). "We showed that, in addition to the previously reported overexpression of PRDM14 in lung cancer, testicular tumors, and lymphoma, PRDM14 is also elevated in esophagus, pancreas, ovary, kidney, and bladder cancers, and is associated with poor survival of patients with breast cancer." (PMID 28423353, 2017). "Other studies have shown that silencing of PRDM14 can suppress tumorigenicity and metastasis potential of breast cancer cells, while methylation-mediated gene silencing of PRDM14 leads to apoptosis evasion in human papillomavirus-positive cancer cells." (PMID 33499882, 2021). "In a panel of breast cancer cell lines and tissue specimens, PRDM14 was highly expressed at both mRNA and protein levels whereas low or no expression was observed in non-cancerous tissues." (PMID 32290321, 2020). "PRDM14 silencing strongly reduced the stem cell phenotype and inhibited breast cancer cell line proliferation, tumorsphere formation, and suppressed cell growth in the presence of low concentrations of anticancer drugs." (PMID 32290321, 2020). "More importantly, PRDM14 was required for the stemness phenotypes of breast cancer cells and induced epigenetic changes finally regulating the expression of genes involved in cancer stemness, metastasis, and chemoresistance." (PMID 32290321, 2020). "As expected, PRDM14 resulted as markedly expressed in cancer tissues and correlated with poor survival of breast cancer patients." (PMID 32290321, 2020). "PRDM14 expression was markedly increased in many different cancer types and correlated with poor survival of breast cancer patients." (PMID 28423353, 2017). "Previously, we showed that PRDM14 is elevated in two-thirds of breast cancers, some of which exhibit gene amplification on chromosome 8q13.3." (PMID 28423353, 2017). "PRDM14 mRNA expression was 3-fold higher in 55.1% (97/176) of breast cancer tissues compared to normal mammary tissues obtained from 10 patients." (PMID 28423353, 2017). "Taken together, these results demonstrate that PRDM14 represses promoter methylation of proto-oncogene and stemness gene promoters in PRDM14-overexpressing breast cancer cells (MCF7 and HCC1937), as it does in ES and primordial germ cells." (PMID 28423353, 2017). "Conditional loss of PRDM14 function also improved survival of MMTV-Wnt-1 transgenic mice, a spontaneous model of murine breast cancer." (PMID 28423353, 2017). "In summary, PRDM14 conferred resistance to chemotherapy and apoptosis, sphere-forming ability, enhanced vascularization, tumorigenicity and metastasis in vivo on breast cancer cells through a similar system to that employed in ES cells." (PMID 28423353, 2017). "In contrast, silencing PRDM14 decreased CSC phenotype-associated biological properties and prevented breast cancer cells from recovering stemness." (PMID 28423353, 2017). "We further examined the potential of a novel breast cancer therapy that modifies PRDM14 expression using an innovative RNAi system - chimera RNAi with CaP hybrid micelles - by systemic injection." (PMID 28423353, 2017).
breast cancer (continued). "PRDM14-transfected breast cancer cell lines also exhibited increased expression of oncogenic microRNAs (miRNAs) (miR-101, miR-155, miR-21, miR-221, and miR-23a) and decreased expression of tumor suppressor miRNAs (miR-128a, miR-200a/b, and miR-520f)." (PMID 28423353, 2017). "Conditional loss of Prdm14 function also improved survival in MMTV-Wnt-1 transgenic mice, a spontaneous model of murine breast cancer containing CSC fractions." (PMID 28423353, 2017). "Since mammary stem cells do not express the estrogen receptor or CK8, but do express CK5/6, our results indicate that PRDM14+ breast cancer cells possess features of mammary stem cell phenotypes." (PMID 28423353, 2017). "The effect of the aberrant methylation of PRDM14 gene has been reported in breast cancer and it is consistent with our results that hypermethylation of this gene plays an important role in many cancers." (PMID 27688749, 2016). "PRDM14 expression is up‐regulated in lymphoma, leukemia, lymphoid neoplasms, non‐small cell lung cancer, as well as in early stages of breast cancer." (PMID 27485778, 2016). "The inducible model is also extremely flexible, and can be used to overexpress Prdm14 in other tissues such as the mammary gland to model solid tumors such as breast cancer." (PMID 24046360, 2013). "Higher levels of PRDM14 expression correlated with the increased methylation state in those breast cancer cells." (PMID 19043588, 2008). "Our prediction of its involvement in the chromatin modification process correlates with the findings of a recent publication that showed that stable expression of PRDM14 up-regulated expression of a variety of genes involved in breast cancer." (PMID 18613947, 2008). "In a screen for differentially methylated loci in human breast cancer epithelial cells, the second intron of PRDM14 had increased levels of DNA methylation." (PMID 19043588, 2008). "Methylation pattern of MAST1, PRDM14, and ZNF177 may represent new diagnostic biomarkers for breast cancer, while methylation of ADCY4, CPXM1, DNM3, PRDM14, PRKCB, and ZNF177 may hold prognostic potential for breast cancer." (PMID 33499882, 2021). "Although PRDM14 expression was associated with poor survival of breast cancer patients, expression was not correlated with breast cancer stage." (PMID 28423353, 2017). "To determine whether the beneficial effects of PRDM14-KD observed in vitro could be translated in vivo, we examined tumor growth in nude mice engrafted with PRDM14-KD breast cancer cells." (PMID 28423353, 2017). "Immunohistochemical analyses showed PRDM14 protein in 37.1% (79/213) of breast cancer patients." (PMID 28423353, 2017). "Silencing PRDM14 reduced the expression of miRNAs upregulated in breast cancer tissues (e.g. miR-106a, miR-149, miR-18a, miR-221, miR-222, miR-224, miR-23a, miR-24, miR-27a/b, and miR-493) and increased expression of those that were downregulated (e.g. miR-15a, miR-150, miR-183, and miR-203)." (PMID 28423353, 2017). "Furthermore, PRDM14 is overexpressed in 57–75% of breast cancers examined and is correlated with genomic amplification at its locus indicating a causative role." (PMID 19043588, 2008). "Overall, we found that MAST1, PRDM14, and ZNF177 had high sensitivity, specificity, and accuracy for the diagnosis of breast cancer." (PMID 33499882, 2021). "Results from additional validation analyses showed that MAST1, PRDM14, and ZNF177 had high sensitivity, specificity, and accuracy for breast cancer diagnosis." (PMID 33499882, 2021). "In summary, we have identified and independently validated abnormal DNA methylation patterns in MAST1, PRDM14, and ZNF177 as potential biomarkers for breast cancer diagnosis." (PMID 33499882, 2021). "As expected, methylation levels of ADCY4, CPXM1, DNM3, GNG4, MAST1, PRDM14, and ZNF177 were found to be increased in breast cancer, and all with p values lower than 0.001." (PMID 33499882, 2021).
breast cancer (continued). "To validate the effects of PRDM14-siRNA treatment, we analyzed Prdm14 knock-out (KO) in MMTV-Wnt-1 transgenic mice, a spontaneous model of murine breast cancer." (PMID 28423353, 2017). "Copy number gain in the genes MED1 (p < 0.001), BIRC5 (p < 0.001), PRDM14 (p = 0.003), and MTDH (p = 0.003) were significantly correlated with high grade male breast cancer." (PMID 22527098, 2012). "Previous studies found that there is elevated expression of PRDM14 in breast cancer, whereas low or no expression was found in non-tumorous cells." (PMID 36982660, 2023). "To further explore the clinical value of these biomarkers, we evaluated whether 6 of our differentially methylated genes—ADCY4, CPXM1, DNM3, PRDM14, PRKCB, and ZNF177—had any relation with overall survival of breast cancer patients." (PMID 33499882, 2021). "PRDM14 expression was also significantly negatively correlated with lymphocyte infiltration in tumors (ρ = −0.52, P < 0.001): PRDM14-negative breast cancer tissues exhibited increased numbers of tumor-infiltrating cytotoxic T lymphocytes (CD3+CD8+CD16–)." (PMID 28423353, 2017). "PRDM14 was detected at varying levels in tumorigenic breast cancer cell lines, but was not present in the non-tumorigenic MCF-10A line derived from benign proliferative breast tissue." (PMID 28423353, 2017). "Survival analysis on 40 tissue samples (high PRDM14 levels: n=21 samples (stage II: n=12, stage III: n = 9), low or undetectable levels: n=19 (stage II: n = 11, stage III: n = 8)) from breast cancer patients showed that PRDM14+ patients had worse prognoses than PRDM14− patients." (PMID 28423353, 2017). "Moreover, silencing PRDM14 reduced the expression of CD44, which imparts cancer stemness, and STAT3, which is required for growth of CD44+CD24– stem cell-like breast cancer cells." (PMID 28423353, 2017). "However, the role of MAST1, PRDM14, and ZNF177 in diagnosis and prognosis of breast cancer remains unclear." (PMID 33499882, 2021). "Our findings add a new layer of evidence to the epigenetic landscape of breast cancer, providing convincing clues that MAST1, PRDM14, and ZNF177 are differentially methylated in breast cancer, as well as that they may serve as potential drivers and biomarkers for breast cancer." (PMID 33499882, 2021). "Moreover, we showed that DNA methylation landscape of ADCY4, CPXM1, DNM3, PRDM14, PRKCB, and ZNF177 could be selected as accurate biomarkers for the prognosis of breast cancer." (PMID 33499882, 2021). "We found that PRDM14 was frequently expressed by CK5+CK8– estrogen receptor-negative breast cancer cells, and that PRDM14 prevented reversal of HCC1937 cells to a stem-like phenotype, suggesting that PRDM14 maintains breast cancer cells in an undifferentiated state." (PMID 28423353, 2017). "Indeed, PRDM14 overexpression has been detected in a variety of human cancer types, including non-small cell lung cancer, T-cell acute lymphoblastic leukemia (T-ALL), high hyperdiploid pre-B-ALL, and breast cancer." (PMID 24046360, 2013). "Similarly, in breast cancer, miR-424 suppresses the cell invasion and stem cell traits under hyperglycemic conditions through the attenuated inhibitory function of miR-424 on CDC42, leading to the activation of PR/SET domain 14 (PRDM14), which is a repressor of pluripotent transcription factors." (PMID 36969009, 2023). "We generated three breast cancer cell lines (MCF-7, MDA-MB-231, and HCC1937) and a non-tumorigenic MCF-10A cell line overexpressing FLAG-tagged PRDM14 to examine the functions of PRDM14 in vitro and in vivo." (PMID 28423353, 2017). "Although PRDM14 and PRDM7 were also among the HMTs with the highest frequency of amplification or homozygous deletion, respectively, in breast cancer, they were excluded from the qRT-PCR analysis because their expression levels in breast cancer cells were too low for detection (data not shown)." (PMID 25537518, 2015).
lung carcinoma (7 papers, 2016 to 2023). "Elevated PRDM14 expression is also associated with acute lymphatic leukemia and lung carcinoma." (PMID 28423353, 2017). "Many reports have described the function of these genes: PRDM14 has been reported to be hypermethylated in lung cancer and has high accuracy in the diagnosis of lung cancer." (PMID 35065650, 2022). "Consistently, PRDM14 overexpression promoted cell migration through extracellular matrix degradation in a human lung cancer cell line." (PMID 32290321, 2020). "The analysis of DNA methylation of a panel of 3 genes (RASSF1A, 3OST2, and PRDM14) in sputum produced a sensitivity of 82 % and a specificity of 66 % for lung cancer detection." (PMID 27777637, 2016). "Similarly, PRDM14 was recently added to a gene panel utilized, also in clinical trials, for the diagnosis of lung cancer through the analysis of DNA hypermethylation of biomarkers in sputum, thus denoting its silencing in these tumors." (PMID 32290321, 2020). "In the last years, PRDM14 has been widely studied in lung cancer." (PMID 32290321, 2020). "Indeed, immunohistochemistry and Western blotting followed by univariate and multivariate analyses were used to examine PRDM14 expression in both primary lung cancers and matched lymph node metastases and to determine the association between its expression and prognosis." (PMID 32290321, 2020). "Evidence has shown that significant PRDM14 methylation occurs in high-grade non-muscle invasive bladder, colon, and lung cancers." (PMID 36982660, 2023). "Interestingly, over 80% of lung cancer specimens contained hypermethylated regions within the promoters of NRN1 and PRDM14 and at the left side of the YTHDF3 promoter." (PMID 27901495, 2017).
pancreatic cancer (7 papers, 2017 to 2023). "Additionally, PRDM14-positive cells were also detected through immunohistochemistry analyses in precursor pancreatic intraepithelial neoplasia and chronic pancreatitis lesions, a pancreatic cancer risk factor." (PMID 32290321, 2020). "PRDI-BF1 and RIZ homology (PR) domain zinc finger protein 14 (PRDM14) function as oncogenes by promoting proliferation, sphere formation, distant metastasis, and chemotherapy resistance in breast and pancreatic cancer." (PMID 37305392, 2023). "PRDM14 is overexpressed in pancreatic cancer tissues and regulates the cancer stem-like phenotypes in pancreatic cancer cells." (PMID 31013960, 2019). "We have previously reported that PRDM14 regulates cancer stem‐like phenotypes in pancreatic cancer cells." (PMID 30338223, 2018). "Although transfection of the binding partners did not also affect each protein's expression 19, these results indicate that upregulation of PRDM14 expression by inflammation in pancreatic cancer cells required other pathways than ER stress." (PMID 30338223, 2018). "We previously reported that inhibition of PRDM14 expression decreases cancer stem‐like phenotypes, including SP cells, in pancreatic cancer cells." (PMID 30338223, 2018). "To validate this in another type of cancer with upregulation of PRDM14, we analyzed tumor growth in nude mice engrafted with PRDM14-KD pancreatic cancer (PK-1) cells." (PMID 28423353, 2017). "Silencing of PRDM14 impairs tumor growth and metastasis in breast and pancreatic cancers." (PMID 37305392, 2023). "The inhibition of PRDM14 has been shown to suppress tumor growth in pancreatic cancer." (PMID 33833773, 2021). "PRDM14 knockdown decreased cancer stem-like phenotypes through upregulation of miR-125a-3p that subsequently downregulated Fyna mechanism that is reported to regulate tumor phenotypes in pancreatic cancer." (PMID 32290321, 2020). "More recently, overexpression of PRDM14 was observed also in pancreatic cancer, where it could sustain cell pluripotency; indeed, PRDM14 knockdown suppressed cancer stem-like phenotypes, including liver metastasis, via miR-125a-3p regulating Fyn expression." (PMID 32290321, 2020). "Moreover, cerulein treatment increased PRDM14 expression in PK‐1 and AsPC‐1 pancreatic cancer cell lines." (PMID 30338223, 2018). "However, single stimulation with cerulein was enough to increase PRDM14 expression in pancreatic cancer cell lines." (PMID 30338223, 2018). "We also assessed PRDM14 expression in cerulein‐treated pancreatic cancer cell lines." (PMID 30338223, 2018). "A normal pancreas may require repeated inflammation for induction of PRDM14 overexpression, while a single inflammation may be enough for already transformed pancreatic cancer cells." (PMID 30338223, 2018). "Moreover, cerulein also increases PRDM14 expression in pancreatic cancer cells." (PMID 30338223, 2018). "A single treatment with ER stress inducers, which increased GRP78, did not increase PRDM14 expression in pancreatic cancer cell lines." (PMID 30338223, 2018). "Although cerulein increased PRDM14 expression in pancreatic cancer cell lines, it did not increase the number of SP cells." (PMID 30338223, 2018).